SMAD4 (SMAD family member 4)
Diseases named in the same sentence as SMAD4 in open-access papers (continued):
Sharing a sentence is not in itself a finding about the gene and the disease.
hepatocellular carcinoma (69 papers, 2013 to 2025). A malignant tumor that arises from hepatocytes. "Overexpression of SMAD4 in hepatocellular carcinoma was associated with poor prognosis." (PMID 29065177, 2017). "Therefore, we tested whether an in vitro system of hepatoma cells could demonstrate a similar association between MyD88 levels and SMAD4/hepcidin expression." (PMID 30234111, 2018). "NEK6, with kinase activity, has been reported to block SMAD4 nuclear translocation and prevent growth arrest in hepatocellular carcinoma cells." (PMID 39256367, 2024). "For example, miR-210 contained inside hepatocellular carcinoma (HCC)-derived exosomes can stimulate angiogenesis by direct inhibition of SMAD4 and STAT6." (PMID 36619866, 2022). "The known mRNA interactors of miR-122 include PKM2, AKT1, MYC, TGFBR1, and SMAD4 in hepatocellular carcinoma, JNK, AP1, and caspases 3/8 in irritable bowel disease, and AKT, PI3K, PCNA, MTDH, PI3K, TRIM29, Bcl-W, CCNG1, and ALDO2 in CRC." (PMID 36499586, 2022). "For example, miR-210 in hepatocellular carcinoma (HCC)-derived exosomes can directly inhibit the expression of SMAD4 and STAT6, promoting angiogenesis." (PMID 34257272, 2021). "It is reported that HEY2 binds to Smad3 and Smad4 promoters to inhibit the transcriptional activity of Smad3 and Smad4, and accelerates the malignant progression of hepatocellular carcinoma through TGF-β/Smad signaling pathway." (PMID 34127651, 2021). "At the same time, miR-130a-3p can also act as an oncomiR in esophageal cancer by inhibiting the expression of SMAD4, which incidentally leads to a tumor suppressor effect in hepatoma cells." (PMID 32971982, 2020). "Accordingly, the Cyclin D1-dependent activation of Smad2/3 and Smad4 is also evidenced in hepatocellular carcinoma (HCC) patients and predicts disease progression." (PMID 33317149, 2020). "This has been evidenced in hepatocellular carcinoma wherein knockdown of SMAD4 reduced migratory capacity and colony formation ability of the cancer cells." (PMID 29861845, 2018). "We show that MyD88 overexpression in Huh7 hepatoma cells increases endogenous SMAD4 protein levels, while conversely, suppression of MyD88 results in lowering SMAD4 levels." (PMID 30234111, 2018). "It has been demonstrated that FHL3 physically and functionally interact with Smad2, Smad3, and Smad4, important regulators of cancer development and progression, and inhibit human hepatoma cell growth in vitro and in vivo." (PMID 24690879, 2014). "Recently, it has been shown that FHL1, FHL2, and FHL3 physically and functionally interact with Smad2, Smad3, and Smad4, important regulators of cancer development and progression, and inhibit human hepatoma cell growth in vitro and in vivo." (PMID 24690879, 2014). "Specifically, miR-181b was activated in response to TGF-β signaling in hepatocellular carcinoma cells, and siRNA knockdown of Smad4 resulted in a decrease in mature miR-181b levels." (PMID 23390484, 2013). "We discovered that overexpressed TAT could increase the expression of cleaved caspase-9, but knocking down Smad2 could decrease cleaved caspase-9 level in hepatoma cell lines, so as Smad3 and Smad4." (PMID 38769521, 2024). "Ubiquitin-specific protease 10 (USP10), which is abnormally activated in a variety of malignant tumor, can bind specifically to SMAD4 and stabilize the effect of SMAD4 by increasing its deubiquitination, and further lead to the metastasis of human hepatoma cells Bel-740286." (PMID 38385079, 2024). "A comparative analysis of miR-122 interactors in different pathways describes the presence of several genes associated with CRC including SMAD4, TGFBR1, AKT, MYC, Rho, Ras, Raf, Bax, and CDK 4/6 to actively engage in hepatocellular carcinoma and other pathways of cancer." (PMID 36499586, 2022). "USP10 promotes hepatocellular cancer metastasis by stabilizing Smad4 protein." (PMID 34412625, 2021).
hepatocellular carcinoma (continued). "Additionally, SMAD4 is a target of miR-146a in various malignancies, such as leukemia and hepatocellular carcinoma." (PMID 27438138, 2016). "Several studies have exhibited the relationship between miR-146a and the risk of hepatocellular carcinoma, and demonstrated highly expressed miR-146a decreased the sensitivity of hepatoma cells to IFN-a treatment through targeting SMAD4, resulting in the suppression of apoptosis." (PMID 27210312, 2016). "SMAD4 is highly expressed in HBV-positive hepatocellular carcinoma patient samples, promotes HCC cell proliferation, and is associated with poor prognosis." (PMID 37685308, 2023). "Current studies have shown that in hepatocellular carcinoma (HCC), exosomal miR-210 secreted by HCC cells can be transferred to endothelial cells, thus promoting tumor angiogenesis by targeting SMAD4 and STAT6." (PMID 37602326, 2023). "USP10 can directly bind to Smad4 and act on the Lys-48-linked polyubiquitin chain on Smad4 to stabilize it; USP10 regulates the abundance and function of Smad4 protein through deubiquitination and activates the TGF-β pathway to further promote the migration of hepatoma cells." (PMID 35875077, 2022). "High rates of deletion and/or mutation of SMAD4 are present in pancreatic cancers and are also reported in lower frequency in colorectal cancer (CRC) and hepatocellular carcinoma (HCC)." (PMID 31744193, 2019). "Recently, it was shown that miR-144 suppresses cell proliferation, migration and invasion in hepatocellular carcinoma (HCC) by directly targeting SMAD4." (PMID 28340489, 2017). "Here, we investigated the functional role of the cyclin D1-dependent activation of Smad2/3 and Smad4 in hepatocellular carcinoma (HCC) CSCs and in HCC primary tumors." (PMID 28415588, 2017). "Similarly, compared to control human hepatoma HepG2 cells, SMAD4 transcript expression was significantly reduced by ∼40% (p<0.05) in cells where miR-224 precursor was introduced and significantly increased by ∼60% (p<0.001) in cells where miR-224 inhibitor was introduced." (PMID 23922662, 2013). "An example of this is the upregulation of TRIM33 caused by the action of circSMAD2 and the following decreased expression of SMAD4, which blocks the TGF-β signaling pathway in HCC (hepatocellular carcinoma) cells." (PMID 41283360, 2025). "SMAD4, a member of the SMAD protein family, exhibits dual roles as both a tumor suppressor and an oncogene in cancers such as hepatocellular carcinoma." (PMID 39182075, 2024). "In hepatocellular carcinoma, miR-125b has an inhibitory effect on EMT and EMT-related features through SMAD2 and SMAD4, which are signal transducers of the TGFβ signaling pathway." (PMID 37443682, 2023). "In contrast, USP10 promotes proliferation and metastasis of hepatocellular carcinoma by targeting YAP/TAZ and Smad4, respectively." (PMID 35277183, 2022). "Increasing studies have linked miRNAs to autophagic regulation during cancer initiation (such as miR-224 targeting SMAD Family Member 4 (SMAD4) in hepatocellular carcinoma (HCC)) and cancer development (e.g., miR-224-3p targeting RB1-inducible coiled-coil protein (RB1CC1) in cervical tumors)." (PMID 34298969, 2021). "Thus, CK1δ and Smad4 are required for FHL1-mediated inhibition of hepatocellular carcinoma (HCC) cell growth." (PMID 32587768, 2020). "A previous study revealed that in SMMC-7221 hepatocellular carcinoma cells, TGF-β inhibited proliferation by upregulating P16 expression and increased apoptosis by activating caspase 3 in a Smad4-dependent manner." (PMID 25890228, 2015). "Notably, lnc-UTGF promoted the TGF-β-stimulated migration of hepatoma cells, whereas this promoting effect was attenuated when SMAD2 and SMAD4 were knocked down." (PMID 34785655, 2021). "Therefore, we suggest that the inhibition of Smad4 and TGF‐β signalling contributes to the DSF/Cu‐induced anti‐metastatic effect and the down‐regulation of EMT in hepatocellular carcinoma cells." (PMID 29148232, 2018).
hepatocellular carcinoma (continued). "Rationale: Sma mothers against decapentaplegic homologue 4 (Smad4) is a key mediator of the transforming growth factor β (TGF-β) pathway and plays complex and contradictory roles in hepatocellular carcinoma (HCC)." (PMID 39346534, 2024). "However, the role in hepatoma is not clear due to the fact that Smad4 overexpression has been reported in patients with extrahepatic cholangiocarcinoma, while reduced expression has been found in patients with intrahepatic cholangiocarcinoma." (PMID 38067256, 2023). "For example, USP10 interacts with and stabilizes YAP/TAZ and SMAD4 to promote the proliferation of hepatocellular carcinoma, while another study indicated that USP10 inhibited the poly-ubiquitylation of AMPKα and PTEN to suppress hepatocellular carcinoma progression." (PMID 35351136, 2022). "Next, analysis of Wnt/β-catenin signaling components revealed that mRNA expression levels of Wnt5A, CTNNB1P1, DVL1, SMAD4, and JUN were detected in well-differentiated hepatoma but not in their para-carcinoma tissues." (PMID 32273945, 2020).
adenoma (66 papers, 2005 to 2025). A neoplasm arising from the epithelium. "Murine adenoma identified Smad4 dependent gene expression signatures that require further evaluation as functional biomarker classifiers of SMAD4 mutated cancer subtypes." (PMID 40348815, 2025). "Patients with SMAD4 DCVs can develop a more aggressive GI phenotype, with polyps associated with low-grade adenoma, high grade adenocarcinoma, upper GI location, and presence of malformed vessels within the stroma." (PMID 38066625, 2023). "Bosman’s hamartoma-adenoma-carcinoma sequence theory postulates a “landscaper” defect, where SMAD4 mutations disrupt epithelial architecture, differentiation, and proliferation via altering the microenvironment." (PMID 38066625, 2023). "Before turning into carcinoma, intermediate adenomas differentiate into late adenomas triggered by mutations in the SMAD4, CDC4, and DCC genes." (PMID 35709138, 2022). "Accordingly, these mouse CRC models induced by mild inflammation reasonably recapitulate the progression of adenoma to adenocarcinoma in sporadic human CRC that is accompanied by loss of Smad4." (PMID 33424832, 2020). "Although all adenomas and Dukes’ stage I colorectal adenocarcinomas expressed SMAD4 protein, progressive loss of SMAD4 protein from Dukes’ stage II to IV colorectal adenocarcinomas were observed." (PMID 29467924, 2018). "SMAD4 somatic mutations have been reported in 0.8% of colon adenomas (the COSMIC database), in 0% of low- and high-grade adenomas and 0% of adenomas and intramucosal carcinomas, indicating SMAD4 mutation is a rare event in early CRC tumorigenesis." (PMID 28179590, 2017). "Besides, histopathological analysis of Smad4‐deficient colon sections revealed severer epithelial barrier disruption, an increased number of adenomas, and the presence of cribriform patterns associated with high‐grade dysplasia." (PMID 37261975, 2023). "Paradoxically, loss of SMAD4 expression has been described to occur typically in later stages of the adenoma to carcinoma sequence, where it is associated with elevated signaling by the TGF-β family, as well as a mesenchymal CRC phenotype, high amounts of stroma, and poor prognosis." (PMID 36436127, 2022). "The adenoma still maintained the benign state after introducing SMAD4 mutation." (PMID 32117908, 2020). "Furthermore, Smad4 loss is also seen in adenomas of patients with familial adenomatous polyposis (FAP), suggesting that it contributes to the progression of CRC in populations at high risk for that disease." (PMID 33424832, 2020).
adenoma (continued). "The reduced viability and altered morphology were accompanied by significantly decreased proliferation and increased apoptosis in Smad4+/+ adenoma relative to Smad4Δ/Δ adenomas when quantified by EdU and cleaved caspase 3 (CC3) labelling, respectively." (PMID 40348815, 2025). "Overall, the suppression of cell cycle genes was evident in Smad4+/+ compared to Smad4Δ/Δ adenomas, as shown by Metascape overrepresentation." (PMID 40348815, 2025). "Conversely, the Lgr5 ISC cluster was significantly enriched in Smad4+/+ (5.8%) compared to Smad4fl/fl adenoma (2.7%)." (PMID 40348815, 2025). "To evaluate the expression of Smad4 mRNA in Smad4Δ/Δ and Smad4+/+ in vitro, we used bulk RNA-seq of adenoma organoids and discovered two different Smad4 mRNA transcripts." (PMID 40348815, 2025). "Immunoblots confirmed expression of Smad4 full-length protein (61 kDa) in both Smad4+/+ and Smad4+/Δ adenomas, with a smaller band of (43 kDa) detected in protein extracts from Smad4+/Δ and Smad4Δ/Δ adenomas." (PMID 40348815, 2025). "TGF-β1 addition (390 pM) resulted in the detection of phosphorylated p-Smad2 and p-Smad3 in both the Smad4+/+ and Smad4Δ/Δ adenomas as expected." (PMID 40348815, 2025). "Thyroid carcinomas demonstrate high immunogenicity compared to adenomas with extensive infiltration by CD8+, CD68+ and CD163+ macrophages, associated with increased expression of SMAD4 and STAT6 in tumor cells." (PMID 39936166, 2025). "Gene expression for Myc was not markedly different between genotypes, yet c-Myc protein levels appeared increased in Smad4Δ/Δ (12–18 h) compared to Smad4+/+ adenomas." (PMID 40348815, 2025). "For subsequent timepoints post-TGF-β1, DEGs were mainly observed in Smad4+/+ adenoma organoids and included Skil, Junb, Serpine 1, Ddit4 and Id1." (PMID 40348815, 2025). "The full-length Smad4 protein in Smad4+/+ adenoma showed nuclear localisation following exposure of 390 pM TGF-β1 for 2 h." (PMID 40348815, 2025). "In culture, Smad4Δ/Δ adenomas appeared smaller and grew slower compared to Smad4+/+ adenomas, as measured by both area and the alamarBlue (AB) growth assay." (PMID 40348815, 2025). "Anti-survivin antibody western blots and nuclear localisation suggested detectable reduction in protein levels in Smad4+/+ adenoma by 18 h post- TGF-β1." (PMID 40348815, 2025). "We discovered that the generation of homozygous Smad4 with Apc LOF alleles was associated with a discordant intestinal phenotype, with adenoma suppression in the small intestine and adenoma progression in the caecum." (PMID 40348815, 2025). "In order to generate an organoid culture, we isolated ApcΔ/ΔSmad4Δ/Δ (Smad4Δ/Δ) and ApcΔ/ΔSmad4+/+ (Smad4+/+) caecal adenoma and generated in vitro cultures in Matrigel using published conditions." (PMID 40348815, 2025). "In Smad4fl/fl, EClpr (0.26% vs 4.1%) and ECepr (1.3% vs 6.5%) were depleted compared to Smad4+/+ adenoma." (PMID 40348815, 2025). "Within 24 h of TGF-β1 administration, > 90% of the Smad4+/+ adenoma cells either had either morphological changes of apoptosis with organoid retraction, or changes in shape toward a spindle or mesenchymal phenotype." (PMID 40348815, 2025). "TGF-β1 induced dose-dependent growth inhibition of both the Smad4+/+ and Smad4Δ/Δ adenomas, but with a 20-fold differential sensitivity." (PMID 40348815, 2025). "The Wnt dependent intestinal stem cell marker Lgr5 was downregulated in Smad4+/+ following TGF-β1 (12 h) compared to Smad4Δ/Δ adenoma (2 log2FC), also suggesting modification in Wnt pathway activity." (PMID 40348815, 2025).